MMP2 (matrix metallopeptidase 2)
Diseases named in the same sentence as MMP2 in open-access papers (continued):
Sharing a sentence is not in itself a finding about the gene and the disease.
tumor (continued). "Notably, the MMP-2-liable POLY-PROTAC NPs displayed half inhibitory concentrations comparable to that of the parental molecule, suggesting that the PROTAC payload can be readily released inside the tumour cells via GSH-mediated cleavage of the disulfide bond." (PMID 35882867, 2022). "In a study, an MMP-2/9-sensitive micelle peptide-conjugated polymerwas developed to improve tumor targeting, accumulation and enhanced loaded drug release at tumor locations, thereby stimulating the antitumor effect both in vitro (MCF-7 and HT1080) and in vivo(tumor-bearing nude mice modelHT1080)." (PMID 35335551, 2022). "MMP2 and MMP9 proteins could rapidly hydrolyze the components of the intercellular matrix and the extracellular basement membrane, and they could destroy the natural barrier of tumor metastasis." (PMID 36144577, 2022). "Moreover, DOX-NPs can stably bind to Bif, whereas in the tumor microenvironment DOX-NPs are more likely to fall off, which may result from the over-expression of matrix metalloproteinase-2 (MMP-2) in tumor tissues." (PMID 35366890, 2022). "Western blot analysis further showed that MG treatment downregulated the expression of vimentin, MMP-2 and MMP-9, and upregulated the expression of E-cadherin and TIMP-2, indicating that MG significantly inhibited the EMT and ECM degradation, and prevented tumor metastasis." (PMID 35770085, 2022). "The combination of MMP2 and TRF could exert a stronger killing effect at the tumor site." (PMID 35600646, 2022). "However, we show that macrophages are responsive to RA and that treatment with RA induces increased activity of MMP-2 while decreasing activity of MMP-9, which may aid in tumor progression." (PMID 34572134, 2021). "The CCL5/CCR5 pathway also supports tumour cell invasion by activating downstream pathways such as PI3K/AKT and calcium/calmodulin-dependent protein kinase II (CaMKII) that ultimately result in the production of matrix metalloproteinase-2 (MMP-2) and -9 (MMP-9)." (PMID 33803414, 2021). "By ulteriorly connecting SCP and Cas9 protein by a dithiocyclopeptide containing MMP-2 sensitive sequence and an intramodular disulfide bond, the yielding Cas9-linker-SCP RNP could induce higher genome editing efficiency in tumor cells compared with normal cells." (PMID 33391496, 2021). "Therefore, TFEB might regulated MMP2 and MMP9 expression through lysosomal biogenesis in the tumor environment." (PMID 33732651, 2021). "Additionally, through Western blotting, we investigated the effect of NLSPE5 on the expression of N- cadherin and E-cadherin and the matrix metalloproteinases MMP-2 and MMP-9 in MDA-MB-231 cells, which are involved in the migratory and invasive capacities of tumor cells." (PMID 34503160, 2021). "In human cancer, tumor cells are not the dominant contributor of MMP-2 secretion to the ECM." (PMID 34429501, 2021). "MMP2 (log2 fold change = 7.47), MMP9 (log2 fold change = 3.63), and TIMP2 (log2 fold change = 2.66) displayed increased expression in the TME, while MMP13 (log2 fold change = −4.41) and TIMP1 (log2 fold change = −2.26) displayed increased expression in the HCC tumor." (PMID 33995488, 2021). "Besides, down-regulation of MMP2 and MMP9 reduced tumor metastasis too." (PMID 34051801, 2021). "We found that in addition to KLF4 and BMI1, miR-135a also inhibited the expression of MMP2 and MMP9, as shown by Western blot, and inhibited MMP activation, as shown by the decrease in the intensity of MMPSense in FMT, which plays important roles in promoting tumor invasion and metastasis." (PMID 33828977, 2021).
tumor (continued). "The findings on the permissive role of Ankrd2 in spheroid formation and in the modulation of MMP2 and MMP9 activities, as well as the evidence that Ankrd2-depleted clones lose the ability to form spheroids, hint at a positive role for Ankrd2 in triggering metastases and tumor spreading." (PMID 33419058, 2021). "Finally, the bioluminescent images and immunostaining of MMP-2, cluster of differentiation 31 (CD31), and the VEGF receptor 1 (VEGFR1) revealed attenuated tumor progression in the combination of the FABP6-knocked-down and temozolomide (TMZ)-treated group in an orthotopic xenograft mouse tumor model." (PMID 34685761, 2021). "At the same time, VOSO4 did not exert any effect on MMP-9/MMP-2 expression in tumour cells." (PMID 33670389, 2021). "Although the reduction of MMP2 was marginal, the reductions in FAK, mesenchymal markers, and MMP9 in Pgrmc1 KO mice may be considered as comprising a challenging environment for the migration of tumor cells." (PMID 33832499, 2021). "Finally, immunofluorescence staining performed by using anti-CD31, -αSMA, -VEGF, -MMP-2 and -MMP-9 antibodies demonstrated a significant reduction of tumor angiogenesis and capability of tumor invasion, when HPR was administered through NL-HPR and, at a greater extent, through NGR-NL-HPR." (PMID 34577553, 2021). "We found that PDC without the MMP‐2‐sensitive linker (PVGLIG) could not achieve the tumor suppressive activity of SynB3‐PVGLIG‐PTX in the GBM cells." (PMID 33552853, 2021). "In addition, the antiangiogenic activity of fucoidan was confirmed in MDA-MB-231 cells through the reduction of VEGFA, IGF-I, MMP-2, and MMP-9 levels, basic fibroblast growth factor (bFGF), and the blockade of the adhesion and extravasation of tumor tissue to vascular endothelial cells." (PMID 34200897, 2021). "Therefore, we hypothesized that MMP-2 enhances the migration ability of CRC and a key modulator of tumor progression from cancer stage I to II." (PMID 34429501, 2021). "On the other hand, AKR1B1 (SMD = 0.3; 95% CI 0.01; 0.60; P < 0.01), CTSK (SMD = 1.52; 95% CI 0.98; 2.06; P < 0.01), MMP2 (SMD = 1.02; 95% CI 0.51; 1.53; P < 0.01), TLR4 (SMD = 0.85; 95% CI 0.34; 1.37; P < 0.01) were up-regulate in cancer groups, which might be the tumor proto-oncogene." (PMID 34646828, 2021). "Altogether, the lack of Mmp2 in F1 tumors promoted a higher tumor control, and the immune landscape was characterized by T cell proliferation (indicated by Ki67 expression) and infiltration of cytotoxic T cells, NK cells, cross-presenting CD103+ DCs, and M1 macrophages." (PMID 34032639, 2021). "As micelles were decorated with anti-PD-1 antibodies via MMP-2 sensitive peptide linker, they could spatio-temporally direct the delivery of anti-PD-1 and PTX by reacting to the MMP-2 molecules being enriched in tumor tissue and lysosomal acidity of tumor cells, respectively." (PMID 33800368, 2021). "Moreover, treatment notably upregulated the mRNA expression levels of GSK-3β, E-cadherin, Bax, Caspase-3, and Caspase-9 and the Bax/Bcl-2 ratio but substantially downregulated β-catenin, N-cadherin, MMP-2, MMP-9, Snail, and Cyclin D1, especially Ki-67 and N-cadherin, in tumour tissues." (PMID 34539401, 2021). "Elemene reduced metastatic tumor nodules in a mouse metastasis model constructed with SGC7901/ADR cells and reduced the expression of miR-1323, Cbl-b, and E-cadherin in the lungs of nude mice, whereas vimentin, MMP-2, and MMP-9 were significantly downregulated." (PMID 34641334, 2021). "Indeed, while soluble MMP2 neither activates nor inhibits CTLX CAR T efficacy, membrane-bound MMP2 expression on tumor cells is needed for successful CTLX CAR T targeting of GBM tumors." (PMID 35011583, 2021). "To summarize our findings, we present a model showing that upregulation of PPFIBP1 promotes FAK signaling and enhances MMP-2 expression via the FAK/Src/JNK axis may through interacting with SRCIN1, and subsequently enhances tumor cell migration and invasiveness." (PMID 34480020, 2021).
tumor (continued). "Furthermore, WB and immunohistochemical assays of the tumor tissue indicated that TQ treatment also upregulated the level of cleaved PARP, E-cad, LC3B and p62 proteins, in the meantime reduced the expression of N-cad, MMP2 and PD-L1 proteins." (PMID 34512159, 2021). "Mmp2 mRNA was expressed by both tumor and stromal cells, but not infiltrating CD45+ cells." (PMID 34032639, 2021). "Association between the expression of EMT-related genes (specifically MMP2 and MMP9) and lncRNAs MALAT1 (study performed on OC tumor tissue samples (n = 64) and reference tissue (n = 30)) and TP73-AS1 (study done on 60 pairs of OC tumor/control tissue) was observed." (PMID 33921525, 2021). "Besides its original role as collagenase and MMP-2 activator, proteomics analysis of human melanoma cells revealed a broad influence of MT1-MMP on the tumor microenvironment, based on the shedding of a variety of adhesion molecules, receptor and transporter proteins." (PMID 34055644, 2021). "It remains unclear why MT1-MMP based activation of secreted MMP2 does not occur in a cis-fashion at the surface of tumor or stromal cells that generates both proteases." (PMID 33740019, 2021). "Further correlationanalysis demonstrated that high MALAT1 expression waspositively related to large tumor size, poor histologicalgrade, terminal stage of cancer and tumor metastasis.Knockdown of MALAT1 inhibited A549 cell growthand invasion, as well as the expression of MMP2 andMMP9." (PMID 31863664, 2020). "Therefore the down regulation of serum MMP-2 and MMP-9 may be a possible action pathway of RGDV-gemcitabine inhibiting tumor metastasis." (PMID 32978501, 2020). "Since MMP2 and MMP9 are involved in the continued growth of the tumor and metastasis, coupled with the fact that high expression of both is related to poor patient survival in various types of cancers, an OV that targets these markers could be of high clinical value." (PMID 33167307, 2020). "In some heterogeneous tumor cells, it may not be integrin α5β3 but other molecules overexpressed, such as MMP2 or VEGFR." (PMID 32724456, 2020). "In the current study, we explored the potential mechanism of Porf-2 in tumor cell migration by screening several key proteins, such as adhesion molecules (ICAM1, VCAM1, E-cadherin), chemokines (CCL4, CXCL4) and their receptors (CXCR4/6/7), integrins (integrin α1/β1/β3), and MMPs (MMP-2/3/7/9)." (PMID 32676454, 2020). "Moreover, high levels of NEK2 were correlated with the tumor nodule number and recurrence, and with the expression of phospho-AKT (V-akt murine thymoma viral oncogene homolog) and MMP-2 (72 kDa type IV collagenase also known as matrix metalloproteinase-2)." (PMID 32294979, 2020). "The association was statistically significant because all the women with higher MMP-2 in the tumor died from the disease, but there was no comparison with low expression, so the competing risk survival curves could not be assessed." (PMID 32669083, 2020). "Abaza and Luqmani found that extracellular low pH could cause the secretion and activation of major proteolytic enzymes, including MMP-2, MMP-9, tissue serine protease, and gelatinase, leading to the degradation of extracellular matrix, thereby promoting tumor invasion." (PMID 32211041, 2020). "The better anti-tumor effect exerted by the combined liposomal therapy compared with each liposomal formulation administered individually could be explained by the dissimilar effect of the two drugs on the production of HIF-1α and MMP-2." (PMID 32340166, 2020). "As MMP‐2 is preferentially accumulated in tumors but not normal tissues, this feature avoids potential side effects of melittin to normal tissues and provides further tumor‐targeting specificity on top of the interaction between AMD3100 and CXCR4." (PMID 32154067, 2020).
tumor (continued). "Likewise, in our in vivo model, the finding suggested that if the in vivo levels of SPARC are low, the expression of MMP-2/9 and p-ERK would be downregulated to suppress the formation and development of ectopic HCC cell tumor, thereby inhibiting the proliferation of the tumor." (PMID 32670867, 2020). "It has also been established that the lack of MMP-2 in mice reduces tumor growth." (PMID 32260356, 2020). "In addition to MMP-2 and TIMP-2, MMP-7 is also relevant for tumor pathogenesis." (PMID 32751899, 2020). "The decrease of serum TNF-α (tumor necrosis factor), IL-8 (interleukin-8), MMP-2 (matrix metalloprotein-2) and MMP-9 (matrix metalloprotein-9) of the treated C57BL/6 mice was correlated with the action pathway of RGDV-gemcitabine inhibiting the metastasis of the planted tumor towards lung." (PMID 32978501, 2020). "Additionally, FSCN1 may regulate nuclear factor-κB (NF-κB) activity, and the expression of MMP-2 and MMP-9, to promote tumor invasion and migration." (PMID 32699531, 2020). "Therefore, Porf-2 may inhibit tumor cell migration through the inactivation of Rac1 via the GAP domain, followed by the down-regulation of MMP-2/9." (PMID 32676454, 2020). "Based on this data, we hypothesize that activation of these tumor promoting genes and increased expression of MMP2 and TGF-β1 proteins in hADSCs-IL2 could have adverse effects on tumor growth when used for the treatment of cancer patients and requires additional investigation." (PMID 32560387, 2020). "Formononetin also demonstrates an inhibitory effect on the expression of matrix metalloproteinases (MMPs) such as MMP-2 and MMP-9 proteins, which play an essential role in the metastatic process of tumor cells as well as the regulation of angiogenesis in the maintenance of tumor cell survivability." (PMID 31402861, 2019). "Interestingly, the selected phage bound to MMP-2 and MMP-9 also specifically homes to tumor vasculature, indicating that (i) that one, or both, of these MMPs is specifically expressed in tumor vasculature and (ii) they are available for phage binding from the circulation." (PMID 31140150, 2019). "CO2 also significantly inhibits tumor growth, tumor new blood vessel formation, and cancer cell invasion by affecting the expression of hypoxia-inducible factor 1-alpha (HIF-1a), vascular endothelial growth factor (VEGF), matrix metalloproteinase-2 (MMP-2), and matrix metalloproteinase-9 (MMP-9)." (PMID 30845750, 2019). "In addition, we observed the increased activity of metalloproteinases (MMP-2 and MMP-12) and levels of the tumor angiogenesis marker VEFG and the lipid peroxidation marker MDA, as well as decreased levels of the non-enzymatic antioxidant GSH and enzymatic antioxidants CAT and GSH-Px in lung tissues." (PMID 31842482, 2019). "The U87MG tumor expressed MMP-2 abundantly, while the Caov3 tumor nearly expressed no MMP-2." (PMID 31346326, 2019). "The observed decrease in MMP-2 expression in tumor together with the increase of feature N simultaneously existed with the expression increase of MMP-2in the stroma and the expression decrease of TIMP-2 in the stroma, as well as the increase in the tumor (P=0.0085)." (PMID 31223594, 2019). "The degrees of expression of two members of the MMP family, MMP-2 (gelatinase-A, 72 kDa) and MMP-9 (gelatinase-B, 92 kDa) were identified to be in closely related relationship with the metastasis and invasion ability of tumor cells, particularly secondary tumor growth." (PMID 30744075, 2019). "However, in the absence of activated MMP-2, the uptake of green fluorescence within the tumor cells was minimal." (PMID 29686590, 2018). "As the downstream effectors of p-ERK, MMP2 and MMP9 are important for tumor invasion and metastasis by degrading basement membrane components, while cyclinD1 acts on G1-S progression of the cell cycle, thus they may decipher the function of CASZ1 in HCC proliferation and metastasis." (PMID 29506567, 2018).
tumor (continued). "Although we could not show the direct binding of M-CTX-Fc to MMP-2, we could show significant difference in the relative tumor growth between the treatment with M-CTX-Fc-L-Dox and that with L-Dox at day 20 (p < 0.05)." (PMID 29495404, 2018). "As our in vitro studies revealed changes in the expression of mesenchymal proteins, Snail and Vimentin, and in the activity of MMP-2 and MMP-9 on cancer cells treated with Kp-10, we also investigated whether the Kisspeptin treatment blocks tumor metastatic behavior in vivo." (PMID 29721201, 2018). "Apart from the influence on the viability of tumor cells, EO could affect migratory and invading properties of different tumor cells through inhibition of MMP-9, MMP-2, focal adhesion kinase (FAK), ERK1/2, and Akt/PKB activation, and partial inhibition of AP-1 and NF-kB transcriptional activities." (PMID 29757198, 2018). "Hence, restraining MMP-2 and MMP-9 levels could influence the invasion and metastasis of the tumor cells, which may lead to the tumor cell apoptosis and interruption of the colon carcinogenic process." (PMID 29419740, 2018). "The very slightly green fluorescence within the tumor cells in the absence of activated MMP-2 might be due to the self-luminescence of the substance within the cells, but not the cellular internalization." (PMID 29686590, 2018). "Trying to get inside to the mechanism responsible for the reduced tumour growth and reduced metastatic formation, we have found that reduced AQP1‐dependent neovessel formation is responsible for HIF‐1α increase, reduced expression of MMP2 and increased expression of caspase‐3." (PMID 29044946, 2018). "MMP-2 and MMP-9 could degrade the ECM and basement membrane collagen of blood vessels then promote tumor cell invasion and matastasis, while vascular endothelial growth by binding to VEGF receptor to promote angiogenesis, thus participating in the development and progression of tumors." (PMID 29156710, 2017). "Moreover, a marked reduction in vascular endothelial growth factor (VEGF) expression, CD31+ blood vessels, CD4+ Foxp3+ Treg cells and the expression of MMP-2, MMP-9, MMP-13 and C-X-C motif chemokine receptor 4 (CXCR4) in the tumour stroma were observed in the Smad3−/− tumour microenvironment." (PMID 28262747, 2017). "Moreover, inhibition of ERK signaling (U0126) imitates MALAT1 overexpression-induced levels of phosphorylated ERK1/2 and MMP2, indicating that the tumor-suppressive function of MALAT1 is mediated by attenuating ERK/MAPK-mediated cell growth and MMP2/9-mediated invasiveness." (PMID 28187439, 2017). "Study has shown that the expression of MMP-2 and MMP-9 is closely related to cancer angiogenesis; tumor cells which can secrete MMP-2 and MMP-9 have high invasion and metastases ability, drugs can also be used to inhibit the growth of tumor cells through lowering the activity of MMP-2 and MMP-9." (PMID 28978315, 2017). "However, MMP-9 likely plays a role in the interaction of CSC and tumour niches, as opposed to MMP-2." (PMID 28606135, 2017). "In addition, when cancer cells with TM4SF1 overexpression were injected into nude mice, this increased the expression of genes related to angiogenesis (uPA, MMP-2, MMP-9 and VEGF), decreased the expression of TIMP (an inhibitor of MMP), and led to promotion of angiogenesis and tumor growth." (PMID 27153056, 2016). "Therefore, we determined the expression of MMP-2 and MMP-9 in tumor sections." (PMID 26517521, 2016). "Besides, we also found that treatment with nifuroxazide could inhibit the expression of MMP-2, MMP-9 and p-Stat3 in A375 tumor tissues." (PMID 26830149, 2016). "Importantly, downregulation of WISP1 in vivo also induced decrease in expression of ICAM-1, VCAM-1, VEGFC, MMP-2, MMP-9 and increase in E-cadherin, suggesting that WISP1 downregulation not only inhibited tumor growth but also suppressed tumor metastasis in vivo." (PMID 27409174, 2016).